SATB1 (SATB homeobox 1)
Diseases named in the same sentence as SATB1 in open-access papers (continued):
Sharing a sentence is not in itself a finding about the gene and the disease.
glioma (continued). "SATB1 expression was also positively correlated with Ki67 expression but negatively with MGMT promoter methylation in glioma tissues." (PMID 22839214, 2012). "In glioma tissues, brown positive staining was mostly homogeneously distributed within the nucleolus, and in the high grade glioma tissues, SATB1 was expressed at increased levels compared to the low grade glioma tissues." (PMID 22839214, 2012). "Cox multivariable analysis showed that SATB1 expression correlated with poor prognosis in patients with gliomas and was an independent prognostic factor." (PMID 22839214, 2012). "Semi-quantitative analysis indicated a significant increase in SATB1 expression in high grade gliomas and low grade gliomas (P=0.001)." (PMID 22839214, 2012). "In the current study, we sought to determine the expression and functional role of SATB1 in gliomas, in order to define the relationship between SATB1, tumor behavior and prognosis." (PMID 22839214, 2012). "Patients showing positive SATB1 expression in high grade glioma had a significantly shorter overall survival period than those with negative expression (P=0.009, log-rank test)." (PMID 22839214, 2012). "The relationship between SATB1 expression, clinicopathological parameters, Ki67 expression and MGMT promoter methylation status was evaluated, and the prognostic value of SATB1 expression in patients with gliomas was analyzed." (PMID 22839214, 2012). "We examined the expression of SATB1 in 70 gliomas and the normal brain tissues using immunohistochemistry." (PMID 22839214, 2012). "Univariate Cox regression analysis also identified that clinical variables including the pathological grade of glioma, SATB1 expression and MGMT promoter methylation were significantly associated with overall survival." (PMID 22839214, 2012). "This study was aimed at investigating the expression and potential role of SATB1 in human glioma." (PMID 22839214, 2012). "SATB1 expression was also positively correlated with Ki67 expression in glioma tissue." (PMID 22839214, 2012). "The percentage of glioma tissues that exhibited positive staining of SATB1 was 62.9%." (PMID 22839214, 2012). "Furthermore, multivariate Cox regression analysis (Forward: LR) was performed to evaluate the potential of SATB1 expression as an independent predictor for overall survival of glioma patients." (PMID 22839214, 2012). "The low expression of SATB1 mRNA and protein were found in the three normal brain tissues and the expression of SATB1 mRNA and protein was increased in the high grade glioma samples compared with the low grade glioma tissues." (PMID 22839214, 2012). "The expression of SATB1 was significantly related to the pathological grade of glioma (P=0.025)." (PMID 22839214, 2012). "The feedback between TCFs and SATB1 can potentially be considered as an essential component of the transcriptional network that regulates the formation of neurospheres by glioma cells, as well as the maintenance of the stemness, migration, and invasion of gliomas." (PMID 36231068, 2022). "SATB1 may have an important role as a positive regulator of glioma development and progression, and that SATB1 might be a useful molecular marker for predicting the prognosis of glioma." (PMID 22839214, 2012). "Our results revealed that a knockdown of SATB1 in highly aggressive glioma U251 cells could alter the expression of c-Met, SLC22A18, caspase-3 and bcl-2 protein, reversing tumorigenesis, inhibiting tumor growth, invasion and angiogenesis, and inducing apoptosis." (PMID 22839214, 2012). "The high SATB1 expression, directly contributing to tumor development and progression, might be a candidate independent prognostic marker for predicting the outcome of human glioma." (PMID 22839214, 2012). "Higher expression of NFKB1 and SATB1, which are involved in regulating PD1 expression was only observed in patients with lower-grade gliomas." (PMID 34305618, 2021).
glioma (continued). "Correlation analysis showed the expression of SATB1 is correlated with MGMT promoter methylation which is a key prognostic factor and can predict treatment response in glioma." (PMID 22839214, 2012). "The Ki67 indexes of glioma tissues with positive SATB1 expression were (49.124.26)%, which were significantly higher than that of glioma tissues without detectable SATB1 expression." (PMID 22839214, 2012). "The 5-year survival rates of patients with positive and negative SATB1 expression in high grade glioma were 0/27 and 2/6 respectively, and there was significant difference in 5-year survival rates." (PMID 22839214, 2012). "The 5-year survival rates of patients with positive and negative SATB1 expression in high grade glioma were 0/27 and 2/8 respectively, and there was significant difference in 5-year survival rates (P=0.007)." (PMID 22839214, 2012). "In addition, knockdown of SATB1 in human non-epithelium- derived cancers such as U251 glioma cells also led to inhibition of cell growth, invasion, metastasis and angiogenesis." (PMID 24047082, 2013).
lung carcinoma (11 papers, 2012 to 2025). "Additionally, loss of SATB1 was proved to be a sign of poor clinical outcome in lung cancer." (PMID 32948197, 2020). "While SATB1’s exact mechanisms in ovarian cancer and lung cancer progression remain under investigation, its role as a negative prognostic factor is well established." (PMID 40071088, 2025). "SATB1 plays a crucial role in lung cancer progression, with varying impacts depending on the histological subtype." (PMID 40071088, 2025). "SATB1 expression in lung cancer correlates with tumor grade, infiltration depth, and lymph node metastasis." (PMID 40071088, 2025). "In summary, SATB1 plays a multifaceted role in lung cancer, with its effects varying according to histological subtype." (PMID 40071088, 2025). "In lung cancer, particularly endometrial cancer, SATB1 expression is significantly higher in cancerous tissues than in non-cancerous tissues." (PMID 40071088, 2025). "The overexpression of miR-191-5p in lung adenocarcinoma downregulates Wnt signaling via the target gene SATB1, thus blocking lung cancer cell migration and proliferation." (PMID 33490103, 2020). "The impact of SATB1′s expression on lung cancer progression seems to be strictly dependent on the exact histological type of the tumour, which is why the distinction between different subtypes is necessary." (PMID 31450715, 2019). "Although some authors suggested a miRNA-mediated SATB1 regulation in lung cancer cells, additional studies are still needed in order to examine this more thoroughly." (PMID 31450715, 2019). "The role of SATB1 in lung cancer has been researched in only a few studies concerning mainly NSCLCs." (PMID 31450715, 2019). "• SATB1 expression level varies in different lung cancer subtypes." (PMID 40071088, 2025). "In lung cancer, higher SATB1 expression has been correlated with improved patient outcomes." (PMID 40071088, 2025). "Research on SATB1 in lung cancer has primarily focused on NSCLC." (PMID 40071088, 2025). "SATB1 has been shown to influence the epithelial-mesenchymal transition (EMT) in lung cancer." (PMID 37540226, 2023). "However, in some subtypes of lung cancer an elevated SATB1 level was revealed to be a positive prognostic factor." (PMID 31450715, 2019). "In our study, we found SATB1 was highly expressed in SCLC tissues and metastatic lymphoid nodes tissues compared with lung cancer adjacent tissue, SATB1-siRNA could effectively inhibit SATB1 expression in SCLC cells." (PMID 23379909, 2013). "Moreover, SATB1′s function and prognostic significance may vary in different lung cancer subtypes due to its heterogeneity." (PMID 31450715, 2019). "The expression of SATB1 in SCLC and metastatic lymph nodes tissues were significantly stronger than that of lung cancer adjacent tissue (p < 0.01)." (PMID 23379909, 2013).
rectal cancer (11 papers, 2012 to 2022). A primary or metastatic malignant neoplasm that affects the rectum. "The analysis of SATB1′s expression in 93 paired samples of rectal cancer and distant normal rectal tissue showed that SATB1 was significantly overexpressed on both the protein and mRNA levels in the cancer samples." (PMID 31450715, 2019). "Recently, SATB1 expression has been shown to correlate with unfavorable tumor characteristics in rectal cancer." (PMID 24971456, 2014). "In a recent study on rectal cancer (n=93), SATB1 expression was found to correlate with a more advanced TNM stage; however, its impact on recurrence or survival was not evaluated." (PMID 22333599, 2012). "Their results indicated that SATB1 may play an important role in human rectal cancer progression." (PMID 31450715, 2019). "Finally, we performed functional experiments and showed that miR-21-5p and SATB1 may be directly involved with poor response to nCRT in rectal cancer patients." (PMID 25496125, 2014). "In a recent study, mRNA and protein levels of SATB1 were found to correlate with unfavourable tumour characteristics in rectal cancer, but the prognostic significance of SATB1 expression was not reported." (PMID 22935204, 2012). "Kaplan Meier analysis revealed no prognostic significance of SATB1 expression for CSS, neither in the full cohort, nor in separate analyses for colon and rectal cancers (data not shown)." (PMID 22935204, 2012).
hepatocellular carcinoma (9 papers, 2013 to 2025). A malignant tumor that arises from hepatocytes. "In line with the present study, we identified the expression of SATB1 in hepatocytes obviously increased during the progression of fibrosis and hepatocellular carcinoma." (PMID 27883059, 2016). "SATB1 is highly expressed in human hepatocellular carcinoma (HCC) tissues and in HCC cell lines with high metastatic potential, driving tumor growth in vivo." (PMID 40071088, 2025). "In this study, we identified SATB1 as a key regulator of T cell exhaustion in Glypican-3 (GPC3)-targeting CAR-T cells within hepatocellular carcinoma (HCC) xenograft models." (PMID 41372119, 2025). "SATB1 overexpression not only reduced expression of multiple inhibitory receptors (PD-1, CTLA-4, TIM3, and LAG-3) but also promoted a central memory phenotype, enhancing cytokine production and cytotoxicity against hepatocellular carcinoma (HCC) cells in vitro." (PMID 41372119, 2025).
breast tumor (8 papers, 2009 to 2022). "SATB1 is a member of the same protein family that has been described as a cancer promoter in breast tumors and has been linked to poor prognosis." (PMID 36351995, 2022). "In cancer patients with poor prognosis, it was proposed that SATB1 gene was able to reprogram chromatin organization and the transcription profiles of breast tumors, which promoted cancer growth and metastasis." (PMID 31783698, 2019). "SATB1 is expressed in a number of aggressive cancer cell lines and poorly differentiated human breast tumor biopsies." (PMID 23251624, 2012). "SATB1, thereby, regulates a large number of genes by folding chromatin into loops and promotes growth and metastasis of breast tumors by reprogramming chromatin organization and altering the transcription of up to 1000 genes." (PMID 23251624, 2012). "SATB1 drives metastasis when expressed in breast tumor cells by radically reprogramming gene expression." (PMID 23251624, 2012). "SATB1, which functions as a genome organizer, plays a pivotal role in promoting breast tumor progression towards metastasis." (PMID 23251624, 2012). "A recent study demonstrated that over-expression of the genome organizer protein SATB1, which is over-expressed in aggressive breast tumors, stimulates CTGF expression." (PMID 21629692, 2011). "Further, SATB1 reprogrammes chromatin organization and gene expression profiles to promote breast tumor growth and metastasis." (PMID 20126258, 2010). "SATB1 in mice contains an AT-hook DNA binding motif and acts as a “gene organizer” to regulate temporal and spatial expression of multiple genes during thymocyte maturation and breast tumor growth and metastasis." (PMID 19956801, 2009). "This ‘genome organizing’ activity of SATB1 is critical for changes in cellular functions such as T cell differentiation, T cell activation, postnatal cortical development, X-chromosome inactivation, epidermal differentiation and progression of breast tumors to metastasis." (PMID 23251624, 2012). "However, to assess SATB1 presence in breast tumor specimens, it is crucial to examine individual tumor cells by immunohistochemistry rather than by total mRNA isolated from whole tissues because in some tumor specimens, SATB1 is expressed in surrounding stromal cells as well." (PMID 23251624, 2012).
liver cancer (8 papers, 2012 to 2025). An epithelial or non-epithelial malignant neoplasm that arises from the liver. "Previous studies have shown that the HBV-encoded HBx and SATB1 may have a crucial role in promoting anoikis resistance and metastasis in HBV-associated liver cancer." (PMID 35847362, 2022). "To assess the in vivo efficacy of SATB1-CAR-T cells, we established a human liver cancer cell line-derived xenograft (CDX) model." (PMID 41372119, 2025). "Downregulated genes in G1 condition were mainly associated with ovarian cancer tumors and xenografts down (dn), ELAVL1 targets up, liver cancer ciprofibrate up, liver cancer E2F1 up, liver cancer ACOX1 up, and SATB1 targets dn." (PMID 41479593, 2025). "The T-lineage enriched global chromatin organizer SATB1 is a close homologue to SATB2, and expression of SATB1 has been reported to correlate with poor prognosis in several cancer forms, e.g. breast, gastric and liver cancer." (PMID 22935204, 2012).
lymph node metastasis (8 papers, 2012 to 2025). "SATB1 expression is associated with stage, invasion depth, lymph node metastasis and distant metastasis." (PMID 28430598, 2017). "Besides, we also discovered that the expression of SATB1 was associated with histologic grade (OR = 1.88, 95% CI: 1.06–3.34), distant metastasis (OR = 1.43, 95% CI: 1.11–1.85) and lymph node metastasis (OR = 1.50, 95% CI: 1.03–2.19)." (PMID 29867574, 2018). "Further studies also showed that the expression of SATB1 in lymph node metastasis was higher than that in primary lesion, and that in distant organ metastasis was higher than that in primary lesion." (PMID 40071088, 2025). "SATB1 overexpression has been observed in epithelial ovarian cancer, where it is positively associated with FIGO stages, lymph node metastasis, and poor prognosis." (PMID 40071088, 2025). "Clinical studies show that SATB1 expression correlates with larger tumor size, poor differentiation, and lymph node metastasis." (PMID 40071088, 2025). "Results showed that patients with high expression of SATB1 tended to develop into lymph node metastasis (OR = 1.50, 95% CI: 1.03–2.19)." (PMID 29867574, 2018). "The multivariate analysis indicated that T stage, TNM stage, lymph node metastasis, SATB-1 expression and SDF-1 expression were independent prognostic factors." (PMID 30337520, 2018). "By combining all the data, we found that patients with high expression of SATB1 tended to have shorter OS and SATB1 was correlated with tumor differentiation, distant metastasis and lymph node metastasis." (PMID 29867574, 2018). "Among the included articles, seven of them with a number of 1772 patients studied the relationship between SATB1 and lymph node metastasis." (PMID 29867574, 2018). "The results of this meta-analysis suggest that SATB1 overexpression is related to advanced stage, lymph node metastasis and distant metastasis." (PMID 28430598, 2017). "SATB1 expression is correlated with classical clinical parameter such as TNM stage, lymph node metastasis, distant metastasis, factors that are associated with a shorter overall survival." (PMID 28430598, 2017). "In all gastrointestinal cancer patients, TNM stage (OR: 1.81, 1.24–2.65), T stage (OR: 1.64, 1.17–2.29), lymph node metastasis (OR: 1.73, 1.26–2.36) and distant metastasis (OR: 1.56, 1.00–2.45) are correlated with SATB1 over-expression." (PMID 28430598, 2017). "Cox multivariate analysis showed that tumor differentiation, depth of invasion, lymph node metastasis, distant metastasis, and SATB1 expression were independent prognostic predictors of CRC." (PMID 24971456, 2014). "We observed that SATB1 protein over-expression was positively correlated with clinical stage (P = 0.025), the status of lymph node metastasis (N classification) (P = 0.018) and distant metastasis (M classification) (P = 0.041)." (PMID 24047082, 2013). "Similarly, an increased SATB1 expression and its correlation with the disease stage, the tumour grade and the presence of lymph node metastasis was also observed in cervical carcinoma." (PMID 31450715, 2019). "Moreover, SATB1′s overexpression was associated with positive HER-2 status, higher TNM stage, and the presence of lymph node metastasis." (PMID 31450715, 2019). "Moreover, the univariate analysis showed that tumor differentiation, T stage, TNM stage, lymph node metastasis, SATB-1 expression, and SDF-1 expression were significantly associated with an increased risk of cancer-related death." (PMID 30337520, 2018). "Moreover, high levels of SATB1 protein expression were positively correlated with clinical stage (P = 0.025), the status of lymph node metastasis (N classification) (P = 0.018), distant metastasis (M classification) (P = 0.041) and LMP-1 expression status (r = 2.35, P < 0.01) in NPC patients." (PMID 24047082, 2013). "It was shown that the level of SATB1 was related to the FIGO stage of the tumour and to the presence of lymph node metastasis." (PMID 31450715, 2019).
lymph node metastasis (continued). "Statistical analysis confirmed that SDF-1 overexpression only correlated with the lymph node metastasis, whereas SATB-1 overexpression correlated with differentiation, T stage, TNM stage, and lymph node metastasis." (PMID 30337520, 2018). "High SATB1 expression was also found to correlate with increased FIGO stage, lymph node metastasis and reduced overall survival, but it was not reported whether SATB1 was an independent prognostic factor." (PMID 22992394, 2012).